HS2ST1 (heparan sulfate 2-O-sulfotransferase 1)
Description:
Catalyzes the transfer of a sulfo group from 3'-phospho-5'-adenylyl sulfate (PAPS) to the 2-OH position of iduronic acid (IdoA) or glucuronic acid (GlcA) within the heparan sulfate (HS) chain and participates in HS biosynthesis (By similarity). Required for metanephric development of kidney formation, suggesting that 2-O-sulfation within HS is essential for signaling between ureteric bud and metanephric mesenchyme (By similarity).
Synonyms: 2-OST; KIAA0448; NFSRA; dJ604K5.2
Tractability: Antibody: UniProt predicts a signal peptide or a membrane-spanning region. PROTAC: ubiquitination databases record sites on it; its protein half-life has been measured.
Gene: Protein-coding gene on chromosome 1 (86,914,635 to 87,109,982, forward strand). Ensembl gene ENSG00000153936.
Subcellular location: Golgi apparatus membrane
Subcellular location (Human Protein Atlas): Mitochondria
Pathways (Reactome):
Metabolism: HS-GAG biosynthesis
Gene Ontology:
Molecular function: heparan sulfate 2-sulfotransferase activity; sulfotransferase activity
Biological process: heparan sulfate proteoglycan biosynthetic process
Cellular component: membrane; Golgi membrane; Golgi apparatus
Genetic constraint (gnomAD): Loss-of-function variants: 12 observed, 28.45 expected, observed/expected ratio (o/e) 0.42, 90% interval 0.27 to 0.68. The upper end of that interval is the gene's LOEUF score, 0.68, which puts it in group 2 of 6, group 1 being the genes least tolerant of losing a copy. Missense variants: 257 observed, 341.64 expected, observed/expected ratio (o/e) 0.75, 90% interval 0.68 to 0.83. Synonymous variants: 115 observed, 124.67 expected, observed/expected ratio (o/e) 0.92, 90% interval 0.79 to 1.08.
Homologues: Orthologues: chimpanzee HS2ST1 (100% identical), macaque HS2ST1 (99% identical), dog HS2ST1 (99% identical), rabbit HS2ST1 (99% identical), pig HS2ST1 (98% identical), mouse Hs2st1 (97% identical), rat Hs2st1 (97% identical), guinea pig HS2ST1 (97% identical), tropical clawed frog hs2st1 (91% identical), zebrafish hs2st1b (85% identical), zebrafish hs2st1a (85% identical), Drosophila melanogaster Hs2st (52% identical), and 1 more. Paralogues in human: UST (28% identical).
Diseases named in the same sentence as HS2ST1 in open-access papers:
HS2ST1 is named in the same sentence as 36 diseases in open-access papers, as found by Europe PMC text mining. Sharing a sentence is not in itself a finding about the gene and the disease. The quoted sentences say what the papers report.
breast carcinoma (4 papers, 2020 to 2024). "Abnormal expression and function of HS2ST1 have been detected in breast cancer, where the upregulation of HS2ST1 is associated with reduced invasive behavior and the cancer stem cell phenotype." (PMID 39062818, 2024). "For example, the upregulation of HS2ST1 was associated with reduced invasive ability by attenuating FGF-2-induced MAPK activation in breast cancer cells." (PMID 39062818, 2024). "Previous studies demonstrated an important role of HS3ST2 and HS2ST1 and the associated changes in HS structure in modulating receptor tyrosine kinase dependent signaling and breast cancer cell invasion, proliferation and senescence." (PMID 33102470, 2020). "Dysregulated expression of HS2ST1 is associated with a CSC and metastasis-associated signature in breast cancer cells carrying a mutation in caveolin, and upregulation of HS2ST1 is associated with reduced invasive behavior and senescence in breast cancer cells." (PMID 33102470, 2020). "In contrast, breast cancer patients with high HS2ST1 expression had a worse prognosis than those with lower HS2ST1 expression." (PMID 39153155, 2024). "Previous studies have confirmed that the HS2ST1-dependent signal transduction pathway determines the cell viability, matrix interaction and invasive behavior of breast cancer." (PMID 36387908, 2022). "The increase of HS2ST1 expression significantly promotes the invasiveness of breast cancer cells, leading to a poor prognosis." (PMID 36387908, 2022). "In addition, the overexpression of HS2ST1 can decrease the stemness phenotype in the triple-negative MDA-MB-231 breast cancer cell line, possibly by regulating the notch and Wnt signaling pathways." (PMID 39062818, 2024). "Our results furthermore show that the overexpression of HS2ST1 and HS3ST2 significantly alters several CSC-related characteristics in breast cancer cells in general, which is worthy of future evaluation in more complex in vivo systems." (PMID 33102470, 2020).
glioblastoma (2 papers, 2017 to 2024). The most malignant astrocytic tumor (WHO grade IV). "HS2ST1 expression was higher in tumor tissues compared with normal tissues in patients with diffuse large B-cell lymphomas, esophageal carcinomas, glioblastoma multiforme, pancreatic adenocarcinomas, rectal adenocarcinomas, skin cutaneous melanomas, stomach adenocarcinomas, and thymomas." (PMID 39153155, 2024).
glioma (2 papers, 2017 to 2024). A benign or malignant brain and spinal cord tumor that arises from glial cells (astrocytes, oligodendrocytes, ependymal cells). "Higher HS2ST1 expression was associated with poor prognoses in patients with kidney chromophobe syndrome, lower-grade gliomas, HCCs, sarcomas, and uveal melanomas." (PMID 39153155, 2024).
allergic asthma (1 paper, 2024). A asthma with a basis in a pathological type I hypersensitivity reaction. "Leukocyte and endothelial cell Hs2st1 deficiencies in a mouse model of allergic asthma enhanced eosinophil recruitment associated with persistent inflammation." (PMID 39153155, 2024).
brain glioma (1 paper, 2024). A malignant glioma that involves the brain. "Patients with high HS2ST1 expression in kidney chromophobe (KICH), lower-grade brain glioma (LGG), LIHC, sarcoma (SARC), and uveal melanoma (UVM) had poor prognoses." (PMID 39153155, 2024).
corpus callosum agenesis (1 paper, 2023). "Furthermore, bi-allelic mutations in HS2ST1, another SCFD2 interactor, have been associated with developmental delay, intellectual disability, corpus callosum agenesis, facial dysmorphism, and skeletal and renal anomalies." (PMID 38025430, 2023).
diffuse large B-cell lymphoma (1 paper, 2024). "Normal tissues adjacent to diffuse large B-cell lymphomas and thymomas expressed very low levels of HS2ST1, suggesting that HS2ST1 can serve as a cancer-specific marker in such patients." (PMID 39153155, 2024).
Ewing sarcoma (1 paper, 2022). A small round cell tumor that lacks morphologic, immunohistochemical, and electron microscopic evidence of neuroectodermal differentiation. "Specifically, we found upregulation of enzymes involved in the catabolism of heparan sulfate proteoglycans (including SGSH, GNS, HS3ST4, HS3ST1, HS2ST1, and HS6ST1) in human Ewing sarcoma." (PMID 35285802, 2022).
hepatocellular carcinoma (1 paper, 2024). A malignant tumor that arises from hepatocytes. "This investigated HS2ST1 expression levels and their prognostic significance in various cancer types, demonstrated the prognostic value of HS2ST1 expression in hepatocellular carcinoma (HCC) patients, and identified molecular signatures associated with HS2ST1 expression." (PMID 39153155, 2024). "We discovered that HS2ST1 expression correlated with poor prognosis in the TCGA-Liver Hepatocellular Carcinoma (LIHC) cohort and was prognostically relevant in two independent International Cancer Genome Consortium (ICGC) cohorts of hepatocellular carcinoma (HCC) patients." (PMID 39153155, 2024).
liver cancer (1 paper, 2020). An epithelial or non-epithelial malignant neoplasm that arises from the liver. "B4GALT2, B4GALT3, DPM1, DPM2, HS2ST1, and PIGS are unfavorable prognostic markers in liver cancer according to the analysis by human protein atlas." (PMID 32850363, 2020).
melanoma (1 paper, 2020). A malignant, usually aggressive tumor composed of atypical, neoplastic melanocytes. "The HS2ST1 gene expression was similar between parental and stem-like melanoma cells, but NDST1 gene expression was elevated at stem-like melanoma cells comparing with parental melanoma cells." (PMID 33196458, 2020).
metastatic tumors (1 paper, 2018). "An overexpression in the transcription levels of the two genes involved, GLCE and HS2ST1, was detected in non-metastatic LSCRCs in this study, although not in metastatic tumors, in contrast to our previous study in RSCRCs which found no alterations in the expression of these genes." (PMID 29940912, 2018).
osteosarcoma (1 paper, 2022). A usually aggressive malignant bone-forming mesenchymal neoplasm, predominantly affecting adolescents and young adults. "We developed a new prognostic risk model for osteosarcoma based on 7 glycolytic genes (INSR, FAM162A, GLCE, ADH5, G6PD, SDC3, HS2ST1) by bioinformatics." (PMID 36387908, 2022). "A risk model based on seven glycolytic genes (INSR, FAM162A, GLCE, ADH5, G6PD, SDC3, HS2ST1) can effectively evaluate the prognosis of osteosarcoma, and in vitro experiments also confirmed the important role of INSR in promoting OS migration." (PMID 36387908, 2022).
tumor (7 papers, 2020 to 2025). "HS2ST1 exhibited higher expression in eight tumor types compared with normal tissues and was associated with poor prognoses in five tumors, including HCC." (PMID 39153155, 2024). "Further work is needed to elucidate the interactions between immune cells and 2-O-sulfated uronic acid residues in heparan sulfate chains and the associations between immune checkpoint proteins and HS2ST1 in the tumor microenvironment." (PMID 39153155, 2024). "Because LIHC is a highly malignant tumor associated with high mortality, we also validated the prognostic role of HS2ST1 expression in HCC." (PMID 39153155, 2024). "In the TCGA-LIHC cohort, 69 primary tumor samples exhibited high HS2ST1 expression and 296 exhibited low expression." (PMID 39153155, 2024). "HS2ST1 exhibited higher expression in osteosarcoma compared with normal tissue, but lower tumor expression levels correlated with poor prognosis in high-risk patients." (PMID 39153155, 2024). "Because the sulfation pattern is typically determined by the cell type in which heparan sulfate is expressed, it is crucial to study the clinical significance of HS2ST1 expression in relation to the specific tumor of interest." (PMID 39153155, 2024). "The aberrant expression of HS2ST1 is frequently observed in tumors, suggesting that HS2ST1 plays an important role in tumor progression." (PMID 39062818, 2024). "Our results demonstrate a novel mechanism by which lncRNA MEG3 can act as a tumor suppressor and regulate endothelial angiogenesis through the exosomal miR-421/HS2ST1 axis, which provides a potential therapeutic strategy for OSCC angiogenesis." (PMID 39062818, 2024). "HS2ST1 expression is dysregulated in several tumor entities, suggesting a role in tumor progression." (PMID 33102470, 2020). "Moreover, HS2ST1 expression levels were inversely correlated with immune cell infiltration in the tumor microenvironment." (PMID 39153155, 2024). "High HS2ST1 expression in HCC tumors was associated with cell signaling that enhanced cell proliferation and protein secretion, as well as changes in immune cell components in the tumor microenvironment." (PMID 39153155, 2024). "For instance, single-cell analysis revealed that the oncogenic genes HS2ST1 and EIF3M are primarily expressed in tumor cells, while the protective gene PPP3CA is mainly expressed in immune cells." (PMID 40951342, 2025). "Our study elucidates the prognostic significance of HS2ST1 expression in HCC patients and provides insights into the potential roles of HS2ST1 in signaling pathways and the tumor microenvironment." (PMID 39153155, 2024). "HS2ST1 and EIF3M likely influence the tumor immune microenvironment by inhibiting NK cell function, whereas PPP3CA may exert protective effects by promoting the infiltration of specific immune cells." (PMID 40951342, 2025). "Heparan sulfate 2-O-sulfotransferase 1 (HS2ST1) catalyzes the sulfation of glucuronic acid residues in heparan sulfate proteoglycans, enabling these proteoglycans to interact with numerous ligands within tumor microenvironments." (PMID 39153155, 2024). "HS2ST1 may regulate the expression of these proteins and thus affect HCC tumor progression." (PMID 39153155, 2024). "HS2ST1 and EIF3M were predominantly expressed in tumor cells, while PPP3CA was mainly expressed in non-tumor cells, such as immune cells." (PMID 40951342, 2025).
cancer (5 papers, 2020 to 2025). A tumor composed of atypical neoplastic, often pleomorphic cells that invade other tissues. "We examined whether HS2ST1 expression was associated with prognosis in various cancers." (PMID 39153155, 2024). "HS2ST1 expression and patient survival data from The Cancer Genome Atlas (TCGA) datasets were analyzed using the Gene Expression Profiling Interactive Analysis (GEPIA) portal." (PMID 39153155, 2024). "Although HS2ST1 plays a key role in cancer progression, its regulation and mechanisms involved in vascular endothelial cells have not been clearly elucidated." (PMID 39062818, 2024). "Among these genes, we were particularly interested in the HS2ST1 gene because previous studies have shown that HS2ST1 plays an important role in cancer growth, movement, and angiogenesis, but the relevant mechanisms are unclear." (PMID 39062818, 2024). "Notably, HS2ST1 emerged as a novel biomarker, potentially promoting cancer stem cell-like properties via heparan sulfate-mediated enhancement of Wnt/β-catenin signaling, highlighting its dual value as both a prognostic indicator and a therapeutic target." (PMID 40951342, 2025). "The roles of HS2ST1 in cancer and the overall immune landscape remain poorly understood." (PMID 39153155, 2024). "HS2ST1 plays an essential role in the migration and differentiation of malignant tumors." (PMID 36387908, 2022). "However, the role of HS2ST1 in cancer remains poorly understood and appears to vary by cancer type." (PMID 39153155, 2024). "However, the prognostic role of HS2ST1 expression in cancer remains unclear." (PMID 39153155, 2024).
inflammation (1 paper, 2024). Aberrant reaction of the microcirculation characterized by movement of fluid and leukocytes from the blood into extravascular tissues. "Previous studies using mouse airway inflammation models also supported an immunosuppressive role for Hs2st1." (PMID 39153155, 2024). "Hs2st1 facilitates immune cell infiltration in mouse models of airway inflammation." (PMID 39153155, 2024).
HS2ST1 also shares sentences with these, for which no sentence is quoted: anaplastic astrocytoma (1 paper); astrocytoma (1); cataract (1); coloboma (1); corneal infection (1); developmental delay (1); esophageal carcinomas (1); infection (1); Intellectual disability (1); iris coloboma (1); neurodegenerative disease (1); Oral Squamous-Cell-Carcinoma (1); pancreatic adenocarcinoma (1); prostate carcinoma (1); rectal adenocarcinomas (1); sarcoma (1); skin cutaneous melanoma (1); stomach adenocarcinomas (1); thymoma (1); uveal melanoma (1).